PPARG (peroxisome proliferator activated receptor gamma)
Diseases named in the same sentence as PPARG in open-access papers (continued):
Sharing a sentence is not in itself a finding about the gene and the disease.
cancer (continued). "In addition, PPARγ has been proven to enhance the radiosensitivity of cancer cells, and agonists of PPARγ have been demonstrated to affect the radiosensitivity of various cancers." (PMID 37170184, 2023). "PPARγ suppresses cancer cell growth via the ERK pathway and induces apoptosis." (PMID 37760347, 2023). "In summary, the pan-cancer analysis and experimental investigations of PPARG have confirmed its differential expression across various types of cancers and its association with survival outcomes and poor prognosis, including in PAAD, LIHC, LGG, GBM, and other types of cancer." (PMID 38044948, 2023). "6-IL acts as a specific ligand of PPARγ that plays an important role in the reduction of cell proliferation and may induce cell death in many types of cancer." (PMID 37373017, 2023). "Furthermore, PPARγ is involved in the regulation of the epithelial–mesenchymal transition (EMT) of cancer stem cells and alveolar lipofibroblast." (PMID 36902342, 2023). "We examined the effect of PPARγ upregulation on glucose uptake efficiency of cancer cells." (PMID 36875279, 2023). "First, we evaluated the PPARG expression in pan-cancer data from TCGA and GTEx." (PMID 37334066, 2023). "The PPARγ role in cancer suppression is unique and intricate." (PMID 36875279, 2023). "Eight targets (EP300, CASP3, CASP8, CHEK2, CREBBP, NOTCH1, PPARG, and TGFBR2) were TSGs (gray text), suggesting that antagonizing these molecules might increase the susceptibility to cancer in healthy individuals." (PMID 37888486, 2023). "This suggests that the upregulation of PPARG may contribute to human cancer development, particularly in these specific types of cancer." (PMID 38044948, 2023). "Activating PPARg suppresses the development of most cancers." (PMID 36681687, 2023). "In addition, we found that up-regulation of PPARγ modulates the Warburg effect and downregulates proliferative cell signalling events in cancer cells." (PMID 36875279, 2023). "PPARγ can be considered a valid therapeutic target in the treatment of various cancers, including AML; in particular, it has been shown that stimulation with pioglitazone, a PPARg agonist, could be highly effective for patients with non-M3 AML." (PMID 38137407, 2023). "The PPARγ, while being a master regulator of lipid metabolism in adipose tissue and the liver, exerts additional regulatory functions in several immune cells, various epithelial cells and cancer." (PMID 37895177, 2023). "Additionally, we investigated the effects of decitabine and/or PBA on programmed cell death and studied the regulation of caspase 3 & 7, PARP and PPARγ after daily treatment of the cancer cell lines for 72 h and in CDA gene knockdown cell lines." (PMID 37208732, 2023). "This is due to its comprehensive action on the pathways responsible for the development and progression of cancer, i.e., the Wnt/β-catenin pathway and PPARγ, as well as its effect on the cell cycle or inhibition of the proliferation of cancer stem cells, which are the main cause of CRC recurrence." (PMID 37446747, 2023). "Furthermore, PPARγ also inhibits cyclin E1 restricted cancer cell progression by inhibiting their entry at G1/S phase in CC cells." (PMID 36875279, 2023). "In addition, to the role of PPARγ in macronutrient metabolism, it is also vital to cancer cell growth regulation." (PMID 38139350, 2023). "However, the role of PPARγ in cancer is somewhat controversial as it was initially thought to have anti-neoplastic effects." (PMID 37250326, 2023). "PPARG has been shown to inhibit cancer cell proliferation and induce apoptosis." (PMID 37491302, 2023). "Summary of the application of PPARγ-targeting drugs (Excitation) in cancer therapy." (PMID 37251321, 2023).
cancer (continued). "Our in vitro data with A02 are in agreement with the literature reports on several malignant cell types, suggesting that PPARγ activation inhibits human carcinoma cell growth by regulating the expression of the cell cycle-associated proteins and inducing terminal differentiation." (PMID 37048080, 2023). "Furthermore, since SPHK1 and peroxisome proliferator-activated receptor-γ (PPARγ) are known to be expressed in human cancers, PPARγ was reported as a transcription factor target for S1P generated by SPHK1, independent of the S1P receptors." (PMID 35565311, 2022). "Thus, activation of PPARγ represents a promising approach to ameliorate cutaneous toxicity in patients with cancer who receive anti-EGFR therapy." (PMID 35324426, 2022). "PPARγ might be the target of a cancer therapy in the near future, and finding new ways to regulate its expression could open the door to the treatment of a number of cancers for which current options are limited." (PMID 36142452, 2022). "SOCS3 transcription is also activated by PPARγ to prevent IL-17-derived cancer growth." (PMID 35652039, 2022). "The role of PPARγ in cancer initiation/progression is contradictory." (PMID 36359869, 2022). "Thus, here, we will describe PPARα and PPARγ functions with respect to the hallmarks of cancer and updates for PPARβ/δ." (PMID 35954274, 2022). "Thus, the combination of MEK inhibitors to enable differentiation with PPARγ agonist, to induce adipogenesis can result in cancer trans-differentiation into bona fide adipocytes." (PMID 36034865, 2022). "Additionally, PPARγ is an important target to treat several types of cancer, neurodegenerative diseases, long-chain fatty acid processing in the intestinal epithelium, body adiposity, mucosal defenses, and hypotensive and anticoagulant effects." (PMID 36092543, 2022). "Some reports evidenced autophagy induction in cancer cells upon PPARγ activation." (PMID 35954274, 2022). "Besides this, rare and potentially pathogenic variants were identified in the DNA repair gene POLN and other cancer-related genes such as PPARG, CTC1, DCC and ALPK1." (PMID 36077770, 2022). "On the other hand, increasing evidence indicates that PPARγ acts as a cancer promoter." (PMID 35690612, 2022). "Thus, it remains difficult to conclude specific PPARγ effects in cancer metabolism from studies using thiazolidinediones." (PMID 35954274, 2022). "The role of PPARγ in metabolism and cancer has been reviewed before." (PMID 35954274, 2022). "PPARγ expression is found in a variety of cancer tissues and cell lines." (PMID 35954274, 2022). "In addition, polyubiquitination of PPARγ was inhibited in USP22 highly expressed cancer tissues compared to adjacent normal tissues." (PMID 35449157, 2022). "Previous studies suggested that PPARγ agonists could directly interfere with the activation of NF-κB and inhibit cancer development." (PMID 36286423, 2022). "PPARγ is highly expressed in adipose tissue (AT), however the effects of pioglitazone to improve insulin sensitivity are also evident in other tissues and PPARγ agonism has been shown to alter cancer derived extracellular vesicle (EV)-miRNAs." (PMID 36120427, 2022). "Indeed, the downregulation of the paired box 8 (PAX8) and peroxisome proliferator-activated receptor gamma (PPARG) genes in PTC tissues leads to the metastasis of cancer cells to lymph nodes and distant tissues." (PMID 36523971, 2022). "Moreover, PPARγ, activated by natural and synthetic ligands, is a promising option for preventing and treating cancer." (PMID 35566291, 2022). "Most of these studies used cancer cell lines and PPARγ agonist treatment in vitro." (PMID 35954274, 2022). "Therefore, not only have we confirmed cell death induction by CBD, we have also confirmed the regulation of vesicle formation by PPARγ in various cancer models." (PMID 35890134, 2022).
cancer (continued). "The pivotal hub genes (mainly PPARG, PTGS2, PTPRC, CDKN2A, and PRKACB) and lncRNAs (e.g., OGFRL1, DGCR5, and LINC01842) have been previously reported to have critical roles in the tumorigenesis of many cancers harboring KRAS mutation." (PMID 35562390, 2022). "Thus, impairment of the regulatory circuit between RBP7 and PPARγ increases the opportunity to promote the occurrence of cancer." (PMID 36276273, 2022). "Interestingly, a positive correlation was found between phosphorylated PPARγ (pS112) and PR (Pearson’s r = 0.45, p < 0.0001), indicating the co-expression of both factors by cold carcinomas." (PMID 36139700, 2022). "In addition, peroxisome proliferator-activated receptor γ (PPARγ) is an antidiabetic target that has a controversial role in cancer therapy." (PMID 34503536, 2021). "Our results showed that EPA-PC and EPA-PE promoted the expression of PPARγ and RXRα, indicating that PPARγ might play an important role in the inhibition of cancer cell development by EPA-phospholipid." (PMID 37073266, 2021). "Although limited evidence is currently available, future studies may need to focus more on such dietary factors, especially for cancers in the digestive tract that have relatively high amounts of bioactive food components and PPARG expression." (PMID 33477496, 2021). "Our data confirms that PAX8/PPARγ rearrangements are cancer specific." (PMID 32638211, 2021). "In contrast, a protumorigenic role for PPARγ has been suggested in a variety of cancers as well." (PMID 33716977, 2021). "Moreover, both PPARγ and DNMT1 are reported to be enriched with mutations in various cancer types (n = 28)." (PMID 34439147, 2021). "Therefore, we conclude that Alp attenuates cancer cachexia and alleviates muscle wasting via activating PPARγ." (PMID 34093209, 2021). "Here, we discuss recent advances focused on the PPARα- and PPARγ-related regulation of non-coding RNAs, histone modification, and DNA methylation in the context of cancer and metabolic and immune-related disorders, as well as the emerging therapeutic potential of these processes in these diseases." (PMID 34638914, 2021). "Interestingly, both cancer progression and lung metastasis can be exhibited by ultraviolet-irradiated apoptotic cancer cells through enhancement of the PPARγ/PTEN signaling in macrophages." (PMID 35047512, 2021). "This unique characteristic fired an enthusiasm to evaluate whether the stimulation of PPARγ in cancer cells could be a promising approach in cancer treatment strategies." (PMID 34549887, 2021). "Nowadays, molecular testing in DTCs suggests a high risk for recurrence of cancer associated with BRAFV600E, RET/PTC 1/3, ALK and NTRK fusions, while the intermediate risk may be related to BRAFK601E, H/K/N RAS and PAX8/PPARγ." (PMID 33922518, 2021). "In conclusion, HSYA could exhibit anti-cancer effect on CRC via activating PPARγ/PTEN/Akt signaling, thereby inhibiting cells proliferation, migration, and invasion in vitro." (PMID 34889713, 2021). "PPARγ and CB1R have been associated to diverse types of cancer." (PMID 33498245, 2021). "In cancer cell models, inhibitory effects could be demonstrated on cancer cell growth by both, PPARγ agonists and PPARγ antagonists as well as apoptotic effects." (PMID 34830351, 2021). "Up-regulation of PPARG expression frequently occurs in many metabolic disorders and cancers." (PMID 33477496, 2021). "Despite the lack of effectiveness of clinical evidence, we speculate that longer term and/or a combined therapy with other anti-cancer compounds may improve anti-tumoral effects of synthetic PPARγ agonists in breast cancer patients." (PMID 34067944, 2021). "Machine learning-powered personalized scoring index comprising 10 PPARγ targets, termed as PPARGi, achieved a near-perfect accuracy in distinguishing cancers from benign tissues, and further identified a small subpopulation of patients at high-risk across different profiling platforms." (PMID 34680260, 2021).
cancer (continued). "The functions of PPARγ in cancer development is ambiguous, and its roles in PDAC carcinogenesis and progression remain unclear." (PMID 35186942, 2021). "ST2 cells treated with serum from cancer cachectic mice showed increased expression of the aP2 and peroxisome-proliferator-activated receptor γ (PPARγ), adipocyte differentiation markers under adipogenic differentiation conditions, compared to ST2 cells treated with serum from control mice." (PMID 33801569, 2021). "As a result, it was speculated that the inhibition of Akt activation that regulated by PPARγ up-regulation was responsible for the cancer suppressor role of HSYA in CRC." (PMID 34889713, 2021). "In addition, accumulative studies have concentrated on the indispensable role of PPARγ in various cancers, such as prostate, breast, hepatic, and bladder tumors." (PMID 34889713, 2021). "Pretreatment with mifepristone, a glucocorticoid receptor antagonist, significantly inhibited the increase in the expression levels of aP2 and PPARγ in ST2 cells treated with the serum derived from LLC-bearing cancer cachectic mice under the adipogenic differentiation condition." (PMID 33801569, 2021). "However, overexpression of PPARγ in cancer cells also leads to modest inhibition of angiogenesis, which suppresses tumor growth." (PMID 34503536, 2021). "The expression of PPARγ in many different types of cancer shows the complexity and the diversity of the biological action of how nitroalkenes overall attenuate inflammation and cancer." (PMID 34946618, 2021). "Indeed, SREBF1 has been shown to be vital to cancer cell proliferation both in vitro and in vivo; likewise, PPARG has been shown to be vital in insulin-stimulated cancer cell proliferation." (PMID 34769312, 2021). "Furthermore, PPARG possess high affinity with the thiazolidinediones (TZDs) class of antidiabetic drugs, supporting its potential role for cancer therapy." (PMID 34567087, 2021). "Besides, CDKN2C and ID2 are downregulated while IL6, BIRC3, PLAT, PPARG, and CEBPB are upregulated in three candidate TCM associated with Transcriptional misregulation in the cancer pathway." (PMID 34490085, 2021). "Several molecular mechanisms for the pro-cancer effect of PPARγ have been proposed." (PMID 33946986, 2021). "The molecular mechanism of PPARG polymorphism and the occurrence and development of cancer has not been elucidated." (PMID 35154340, 2021). "However, the biological significance of PPARγ in cancer development and progression is far from completely understood and for some cancers appears to be even inconsistent and contradicting." (PMID 33716977, 2021). "Many cancer stem cells are also sensitive to the terminal differentiation directed by PPARγ." (PMID 33946986, 2021). "In cancer, the tumorigenic role of PPARγ remains highly controversial." (PMID 34680260, 2021). "Activation of PPARγ by agonists such as thiazolidinediones has been shown to have, in vitro and in vivo, anticancer effect in many cancer types reducing cell proliferation and preventing differentiation in cancer cells." (PMID 33728291, 2021). "Here, we used PPARγ agonist Rosiglitazone or PPARγ antagonist T0070907 to intervene the PPARγ pathway and to investigate whether pharmacological activation or inhibition of PPARγ would affect the cancer cell survival." (PMID 35186942, 2021). "The anti-inflammatory role of PPARγ in myeloid-lineage cells has been reported to be important in controlling pro-inflammatory cytokine synthesis, myeloid-derived suppressor cell expansion, immunosuppression, and cancer development." (PMID 33995008, 2021). "Molecular testing in DTTs documents a high risk for recurrence of cancer associated with BRAFV600E, RET/PTC 1/3, ALK and NTRK fusions, while the intermediate risk may be related to BRAFK601E, H/K/N RAS and PAX8/PPARγ." (PMID 33922518, 2021). "Furthermore, PPARG inducing the down-regulation of Wnt/beta-catenin pathway was observed and aberrant in many cancers." (PMID 34384030, 2021).
cancer (continued). "Interestingly, it has been shown that PPARγ reduces the expression of the HDACs in carcinomas cells, and that the expression of PPARγ is reduced by oxidative stress." (PMID 34203655, 2021). "The effect of PPARG expression on patient clinical outcome thereby depended on the cancer type." (PMID 32024906, 2020). "One of the mechanism responsible for the induction of apoptosis in cancer cells is the stimulation of peroxisome proliferator-activated receptor-γ (PPARγ) by several factors, i.e. prostaglandins, glitazones and fatty acids (including CLA, which is its natural ligand)." (PMID 31993929, 2020). "In fact, the use of PPARγ agonists in human cancer therapeutics has been studied." (PMID 32054125, 2020). "The abnormal activation of the PPARγ/RXRα pathway decreases the activity of immune cell infiltration by inhibiting the expression and secretion of inflammatory factors, thereby hampering immunotherapies using immune checkpoint blockade in patients with cancer." (PMID 33266062, 2020). "In addition, PPARγ has also shown to play an important role in the regulation of cancer cell growth due to its anti-proliferative and pro-apoptotic properties." (PMID 32982759, 2020). "Taken together, our results suggest that CB11, a novel PPARγ agonist, may be a novel anti-cancer agent, and it could be useful in a therapeutic strategy to overcome radio-resistance in radiation-exposed NSCLC." (PMID 32958825, 2020). "In the difficulty of well-known anti-cancer drugs, we developed a novel PPARγ agonist CB13 (1-benzyl-5-(4-methylphenyl) pyrido [2,3-d]pyrimidine-2,4(1H,3H)-dione) and investigated the anti-cancer effect and cell death mechanism on human non-small cell lung cancer (NSCLC) cells." (PMID 33051435, 2020). "In addition to cell cycle arrest, the induction of autophagy is a major effect of PPARγ in cancer cells, as observed in colon, breast, bladder, and adrenocortical cancer cell lines." (PMID 32708786, 2020). "Furthermore, there have been clinical trials for various cancers using PPARγ agonists such as pioglitazone." (PMID 33266062, 2020). "In addition, these acetylenic oxylipins have shown to act as ligands for the nuclear receptor PPARγ, which play a central role in growth, differentiation, and apoptosis of cancer cells." (PMID 32486470, 2020). "Although the PPARγ activation contributes to the pro-apoptotic phenotype of cancer cells, the molecular mechanism of this process in still unknown." (PMID 32710395, 2020). "For example, high PPARG expression was shown to be associated with decreased risk for BRCA and increased risk for CESC in the gynecologic organ system, and decreased risk for READ/STAD and increased risk for LIHC/PAAD cancers in the GI organ system." (PMID 32024906, 2020). "The MEX3A‐mediated regulation of PPARγ signalling might also have a yet undisclosed significance for intestinal pathologies, namely cancer initiation/progression." (PMID 32052574, 2020). "On the other hand, PPARγ was shown to be expressed in human colonic mucosa and cancer." (PMID 32028670, 2020). "These properties make PPARg agonists attractive candidates for anti-cancer drugs." (PMID 32850012, 2020). "PPARγ activation with thiazolidinediones could therefore have deleterious effects in patients with cancer." (PMID 32785018, 2020). "PPARα and PPARγ have also been suggested as mediators of the anti-angio- and tumorigenic effects of pomegranate extract as their respective antagonists abolished the beneficial effects of pomegranate extract on cancer vascularization and growth." (PMID 32785018, 2020). "Notably, HIF1α can activate the Wnt pathway, stimulating the self-renewal of BCSCs through a direct activation of cancer stemness capability, but also inhibiting PPARγ activity." (PMID 33352766, 2020). "We investigated whether the anti-cancer effect of PPARγ is through regulating TLR4 signaling pathway." (PMID 32665906, 2020). "This highlights a link between PPARγ, inflammation and cancer." (PMID 31936729, 2020).